CCL5 (C-C motif chemokine ligand 5)
Diseases named in the same sentence as CCL5 in open-access papers (continued):
Sharing a sentence is not in itself a finding about the gene and the disease.
melanoma (continued). "Four of these Top HRLs are recognized by 2 of the Top HRs and represent ligand-receptor pairs that have been previously identified as crucial mediators of T and B cell trafficking in melanoma: CXCL10 and CXCL9 are ligands for CXCR3; and CCL4 and CCL5 are ligands for CCR5." (PMID 34454518, 2021). "Similarly, CCL5 is capable of inducing Treg cell infiltration in the TME, as well as stimulating melanoma and prostate cancer cell proliferation." (PMID 35008589, 2021). "Recent evidence suggests that CCL4 and CCL5, but not CXCL9-11, are positively associated with survival in melanoma." (PMID 32841222, 2020). "For example, in melanoma, the lack of CCR5 ligands (CCL3, CCL4, CCL5) and CXCR3 ligands (CXCL9 and CXCL10) has been associated with limited infiltration of antigen-specific T cells." (PMID 30873179, 2019). "Moreover, therapies such as dacarbazine and temozolomide induce the CD8+ T cell chemoattractants CCL5, CXCL9, and CXCL10 in human melanoma cell lines." (PMID 30899263, 2019). "CCL5 and CCR5 are expressed by melanoma cells, primary melanomas, and cutaneous metastasis." (PMID 24523569, 2014). "Thus, we hypothesized that IκBζ might repress CXCL9, CXCL10, and CCL5 expression through the interaction with EZH2 and/or HDAC3 in melanoma." (PMID 40562773, 2025). "Although increased STAT3 and NF-κB activity in IκBζ-expressing melanoma could explain the elevated expression of IL-6 and IL-1 cytokines, STAT3 and NF-κB inhibition was unable to recover IκBζ-mediated suppression of Cxcl9, Cxcl10, and Ccl5 in melanoma cells." (PMID 40562773, 2025). "In mouse melanoma models, eosinophil recruitment induced by Tregs depletion or by IL-33 treatment mediated melanoma regression through production of CD8+ T cell attracting chemokines (i.e., CXCL9, CCL10 and CCL5) by promoting tumor-reactive CD8+ T cell responses." (PMID 40050933, 2025). "In a melanoma model, HIF−1α inhibition was also shown to increase the accumulation of natural killer (NK) cells and CTLs in the tumor bed by upregulating chemokines such as CCL2 and CCL5, thereby enhancing the effectiveness of anti−PD−1 therapy and peptide vaccines." (PMID 40297580, 2025). "Finally, we observed a significant negative Spearman correlation (r = −0.4021; p = 0.0376) between the two Down-miRs (i.e. miR-204-5p and miR-199b-5p) and the four Up-genes (i.e. VEGFA, TGFβ1, CCL5 and CXCL2) only in melanoma biopsies progressed after targeted therapies (PD samples)." (PMID 36418472, 2023). "While Bcl-xL overexpressing melanoma cells silenced for CCL5 do not show less ability to invade the tail, inhibition of CCL5 significantly reduced the capacity of macrophages to be recruited at the tumor site, resulting in reduced interactions between invading melanoma cells and macrophages." (PMID 37488586, 2023). "We speculate that LCMV treatment alone is potentially not sufficient to upregulate CCL5 expression in the B16 syngeneic melanoma model." (PMID 32973762, 2020). "Moreover, it was recently found that CCR5 is expressed on MDSC in RET transgenic melanoma-bearing mice and melanoma patients, playing an important role in their recruitment to the tumor microenvironment via the CCR5 ligands (CCL3, CCL4, and CCL5)." (PMID 29942309, 2018). "This review summarizes updated information on the role of the CCL5/CCR5 axis in tumor development and/or progression, focusing primarily on multiple myeloma (MM), classical Hodgkin lymphoma (cHL), prostate, breast, gastric, colon, and ovarian cancer, and melanoma." (PMID 24523569, 2014). "Thus, our results support a model in which IκBζ-mediated recruitment of EZH2 and HDAC3 represses Cxcl10, Cxcl9, and Ccl5 in melanoma, contributing to the observed lack of T-cell infiltration and immunotherapy resistance in the α-PD-1-treated, IκBζ-expressing melanoma mouse models." (PMID 40562773, 2025).
melanoma (continued). "Besides, Ocoxin reduces the secretion of proinflammatory mediators LGALS1, OPN, CCL5, and CCL9 chemokines by melanoma cells, which could result in a reduction of the recruitment and differentiation of mesenchymal stem cells into CAFs and decreased resistance to anticancer drugs of cancer cells." (PMID 33669949, 2021). "It was discerned that within Flu treated B16-F10 melanoma sites, there were no alteration in the levels of CCL2, CCL3, and CCL5, which are pivotal in mediating neutrophil recruitment." (PMID 40226609, 2025). "Dedifferentiated melanoma cells have been reported to secrete multiple cytokines in greater quantity, notably CCL2, CCL5 and IL-1β, either without inflammatory stimuli or when stimulated with TNFα." (PMID 39736644, 2024). "Moreover, a cohort study in melanoma tissues revealed negative associations between intratumoral members of the genera Algibacter and Epilithonimonas and CD8+ T cell infiltration, while the Algibacter genus was also negatively correlated with overexpression of the chemokines CXCL9, CXCL10 and CCL5." (PMID 39120310, 2024). "Most secreted factors (TNFα, GM-CSF, G-CSF, PDGF-BB, CCL5, CCL11, IL-3, IL-6) were not induced by exogenous IFNγ in our panel of melanoma cells, confirming the complex inflammatory signaling profile of de-differentiated PD1 PROGs with intrinsic IFNγ signaling." (PMID 36934113, 2023).
viral infection (178 papers, 2007 to 2026). "Several studies demonstrated earlier that the expression of chemokines, such as Ccl2, Ccl3, Ccl4, Ccl5, and Cxcl10, during viral infection is associated with enhanced trafficking of leukocytes into the brain." (PMID 34379515, 2021). "As expected from the delay in the start of viral replication, CXCL10, and CCL5 responses were delayed in the brainstem compared with the lungs, reflecting the discrepancies in cell susceptibility to viral infection in the two tissues." (PMID 34608167, 2021). "CCL5 is often referred to as a “double-edged sword” because it plays crucial roles in immune cell recruitment and activation that clear acute viral infections, yet CCL5 can also cause chronic inflammation that contributes to pathogenesis." (PMID 34399621, 2021). "Our observations indicate that PRINS is up-regulated during stress and influences local inflammation through the regulation of CCL5, which is well known as a key pro-inflammatory chemokine and is associated with viral infection." (PMID 32998396, 2020). "Inflammatory mediators MCP1 (CCL2), RANTES (CCL5) and IP-10 were found to be elevated in alcoholism, which has been reported previously in association with alcoholism-related viral infection, alcoholic liver and pulmonary disease." (PMID 27043532, 2016). "Furthermore, CVB3-stimulated microglia produced pro-inflammatory cytokines and chemokines, including Il-6, Ccl5, and Cxcl10, underlining their crucial role in orchestrating immune responses during viral infection." (PMID 41503211, 2026). "Highly pathogenic H5N1 viral infection in human macrophages induced higher expression of IL-6 and CCL5 (RANTES) than pH1N1, which may explain generally mild clinical disease among H1N1pdm-infected patients." (PMID 22279582, 2012). "Induced by a series of other cytokines as IL1A (IL1A fold regulation = 2.99), IL1B (IL1B fold regulation = 10.76), IL7, TNF (TNF fold regulation = 2.39), LPS or viral infections, CCL5 behaves like a proinflammatory cytokine." (PMID 40149697, 2025). "Conversely, USP5 deficiency facilitated the virus infection-triggered transcription of IFNB, ISG54, and CCL5." (PMID 39761299, 2025). "Limited changes were seen in the expression of CCL-3 and CCL-5, chemokines that are often raised in viral infections and help recruit both NK cells and macrophages." (PMID 39000027, 2024). "An increase in CCL5 levels in milk is expected because this chemokine is produced early during virus infection and can also be induced later in response to TNF-α and IFN-γ produced by CD4+ and CD8+ T cells, epithelial cells, fibroblasts, and platelets." (PMID 39867906, 2024). "CCL5 has been shown to play a key role in the immune response to viral infection, as it is degranulated from activated HIV-specific CD8+ T cells along with perforin and granzyme A." (PMID 39119291, 2024). "Overall, our study provides novel evidence of an NK cell/CCL5 mediated response to peripheral viral infection during a postnatal sensitive period of the developing cerebellum." (PMID 39175524, 2024). "In comparing the two viral infections, CCL5, an inflammatory cytokine, was significantly elevated at both the 24 and 48 hpi timepoints for ZIKV infections, consistent with the RNAseq data." (PMID 38440980, 2024). "Further, CCL5‐positive anatomical structure exhibited highly enrichment on inflammation pathway (Chemokine signaling, IL‐17 signaling, virus infection) and neuronal activity‐related pathway (GABAergic synapse, calcium reabsorption, dopaminergic synapse)." (PMID 36440924, 2023). "CCL5 was initially described as T cell-derived chemokine that attracts and activates T cells and plays an important protective role in viral infections." (PMID 38054006, 2023). "It is important to note that CCL5/RANTES is a chemokine important for T-cell homing and migration during acute virus infections." (PMID 37881339, 2023).
viral infection (continued). "An initial connection between CC chemokines (β-chemokines) and viral infections was made with the discovery that RANTES, macrophage inflammatory proteins MIP-1α, and MIP-1β (also known as CCL5, CCL3, and CCL4) effectively suppress HIV-1." (PMID 36839838, 2023). "A previous study found that a ligand of TLR3 contributes to the viral-infection-induction of chemokine CCL5/RANTES secretion by airway epithelial cells to attract inflammatory cells." (PMID 35563088, 2022). "C-C motif chemokine ligand 5 (CCL5) has been identified as a chemokine that is localized in white matter tracts undergoing demyelination following viral infection." (PMID 36235456, 2022). "Here, we show that CXCL10, CXCL11 and CCL5 known to be expressed in the CNS during various viral infections including those by encephalitic arboviruses were upregulated by either virus, pointing to the induction of a strong inflammatory response." (PMID 33799906, 2021). "The different consequences of PKR on Mx1, ISG15, and CCL5 expression kinetics suggest that, although all these genes are overall upregulated upon viral infections, they are also differently tuned by additional host factors such as PKR." (PMID 34372519, 2021). "CCL5 is a chemokine expressed in many cell types in response to viral infections and IFN-β, and plays a pivotal role in migration of effector and memory T cells." (PMID 34372519, 2021). "As further evidence for TRIM41-mediated virus-triggered interferogenic response, we found that TRIM41 deficiency impaired the induction of interferon-stimulated genes (ISG), such as Cxcl10, Ccl5, and Ifi202b, by virus infections." (PMID 33640899, 2021). "We regardthis experimental setup as a characteristic in vitro model of airway disease, because CCL5 production is clinically observed in patients with repeated viral infections, eosinophilic asthma, and persistent Th2‐type inflammation." (PMID 33534941, 2021). "The remaining 20 non-targetable SARS-CoV-associated disease genes include proteins (e.g., CD14, IFNA1, IFNB1, IL4, IL10, CCL5) having key roles in the immune-inflammatory response to viral infection as well." (PMID 33544720, 2021). "In a BCSFB model using human choroid plexus papilloma cells, a viral infection with Echovirus 30 showed an enhanced secretion of Cxcl1, Cxcl2, Cxcl3, and Ccl5." (PMID 32645014, 2020). "Ccl-5 is highly expressed in bacterial and viral infections and it recruits neutrophils to the site of inflammation." (PMID 33122795, 2020). "The results demonstrated that carvedilol promoted the production of Ifnb, Isg15, and Ccl5 and reduced the virus titers in the spleens, livers, and lungs of WT mice after virus infection." (PMID 33243993, 2020). "Taken together, these data demonstrate that the CHPV-induced expression of CXCL10 and CCL5 is triggered at the stage after viral infection." (PMID 30001342, 2018). "In contrast, virus infection increased only CCL5 levels in both cell types at mRNA and peptide levels 24 h after infection [Suppl." (PMID 30027450, 2018). "In mild persistent asthmatics, viral infection was associated with increased protein abundance of CXCL10, sICAM-1, CCL2, CCL4, CCL5, CCL20 and CCL24." (PMID 30463560, 2018). "The levels of either gene expression or cytokine proteins (IL-1α, TNFα, IL-6, CXCL10, CCL5, CCL2, CCL3, CCL4, and CCL5) in RSV-infected PMФ are comparable to the H5N3 virus infection." (PMID 28558796, 2017). "The choice of cytokines was based on the known role of these molecules in the context of neuropathology, either by mediating inflammation (IL-6, IL-1β, TNFα, CCL5, CXCL1) and/or by their association to viral infections (IFNs)." (PMID 28330482, 2017). "CCL5 is a chemokine and an important inflammatory mediator; CCL5 regulates diseases due to viral infection by signaling via CCR5 on CD8(+) T cells and modulates anti-viral activities." (PMID 25550087, 2015).
viral infection (continued). "Most of these proteins were significantly upregulated at 64 hpi in response to the viral infection, while some were first upregulated at 48 hpi, including CCL5 and TGF-β1." (PMID 25333634, 2014). "The high molecular weight RNA was used to ensure that virus infection induced robust cellular antiviral mRNA responses by RT-qPCR, as indicated by induction of the antiviral chemokine CCL5." (PMID 24086750, 2013). "To confirm that loss of MAVS is responsible for increased cytokine production induced by γHV68, we “reconstituted” MAVS expression by lentivirus in Mavs−/− MEFs, and examined gene expression of cytokines (such as TNFα and CCL5) in response to viral infection." (PMID 22110409, 2011). "It has demonstrated that many viruses, including influenza A virus, activate the PI3K/Akt signal pathway and this pathway has been shown to be involved in CCL5 retinal expression in human pigment epithelial cells after viral infection." (PMID 19592477, 2011). "CCL-5/RANTES production from bronchial epithelial cells contributes to infiltration of inflammatory cells in the airway during viral infection." (PMID 21108843, 2010). "Importantly, CCL2 and CCL5 are known to drive inflammatory monocyte infiltration into the brain during viral infection, supporting a key role of these chemokines on inflammation." (PMID 41139159, 2025). "Consistent with previous studies, we discovered that CCL5 expression was markedly elevated in the HIV infection group, which may be connected to the activation of cellular immune responses caused by viral infection." (PMID 39119185, 2024). "Changes in the expression of CCL-3 and CCL-5, chemokines associated with acute viral infection, were non-significant and showed little difference between the two arms." (PMID 39000027, 2024). "Strong IFN signaling responses observed in acute viral infection are often accompanied by induction of genes associated with cell stress (DDIT3/CHOP), apoptosis (PMAIP1/Noxa), and general inflammatory chemokines (CXCL10, CXCL12, and CCL5)." (PMID 38440980, 2024). "In particular, RANTES/CCL5 seems to be almost invariably enhanced during viral infections." (PMID 39061002, 2024). "Inflammatory gene sets, and individual inflammatory maker genes CXCL10, CXCL11 and CCL5, were significantly increased in the buffer-only treated cultures from 24 hours to 48 hours, in a viral dose-dependent manner, indicating that the virus infection drives this expression over time." (PMID 39621805, 2024). "CCL5 is a chemokine that is expressed initially in viral infection." (PMID 36548828, 2022). "CCL5 is a T cell chemoattractant that is critical for immune control of viral infections." (PMID 35658050, 2022). "In addition, IL-32θ negatively regulates CCL5 expression, an inflammatory chemokine secreted in several conditions such as viral infection and cancer, at both mRNA and protein levels." (PMID 35281066, 2022). "CCL5 also plays a key role in the immune response to viral infection." (PMID 34439908, 2021). "CCR5 plays important roles during influenza infection by contributing to a suitable immune response via CCL5 to cope with the viral infection, but also subsidizing excessive inflammation and tissue damage by mechanisms associated with increased CCL3 production." (PMID 35126379, 2021). "The release of CCL3, CCL4, and CCL5 may promote the recruitment and activation of T cells during viral infection of the brain." (PMID 34399779, 2021). "RPE in vivo may produce CCL5 and other cytokines in culture for instance in response to viral infection." (PMID 32765507, 2020). "CCL5 is another interesting chemokine with antiviral action: indeed, in a murine model, CCL5-overexpressing NK cells were hyperactivated and made animals resistant to the viral infection." (PMID 33014780, 2020).